THBS4 (thrombospondin 4)
Description:
Adhesive glycoprotein that mediates cell-to-cell and cell-to-matrix interactions and is involved in various processes including cellular proliferation, migration, adhesion and attachment, inflammatory response to CNS injury, regulation of vascular inflammation and adaptive responses of the heart to pressure overload and in myocardial function and remodeling. Binds to structural extracellular matrix (ECM) proteins and modulates the ECM in response to tissue damage, contributing to cardioprotective and adaptive ECM remodeling. Plays a role in ER stress response, via its interaction with the activating transcription factor 6 alpha (ATF6) which produces adaptive ER stress response factors and protects myocardium from pressure overload. May contribute to spinal presynaptic hypersensitivity and neuropathic pain states after peripheral nerve injury. May play a role in regulating protective astrogenesis from the subventricular zone (SVZ) niche after injury in a NOTCH1-dependent manner (By similarity).
Synonyms: TSP4; TSP-4
Tractability: Antibody: its Gene Ontology location is reachable by antibodies, with high confidence; UniProt places it where antibodies can reach, with medium confidence; UniProt predicts a signal peptide or a membrane-spanning region.
Gene: Protein-coding gene on chromosome 5 (79,991,311 to 80,083,831, forward strand). Ensembl gene ENSG00000113296.
Subcellular location: Endoplasmic reticulum; Sarcoplasmic reticulum; Secreted; Secreted, extracellular space; Secreted, extracellular space, extracellular matrix
Subcellular location (Human Protein Atlas): Vesicles; Predicted to be secreted
Pathways (Reactome):
Signal Transduction: Signaling by PDGF
Gene Ontology:
Molecular function: calcium ion binding; heparin binding; integrin binding; protein binding
Biological process: endothelial cell-cell adhesion; myoblast migration; negative regulation of angiogenesis; positive regulation of endothelial cell proliferation; positive regulation of neutrophil chemotaxis; positive regulation of peptidyl-tyrosine phosphorylation; behavioral response to pain; regulation of tissue remodeling; response to endoplasmic reticulum stress; cell adhesion
Cellular component: basement membrane; extracellular exosome; extracellular region; endoplasmic reticulum; extracellular matrix; sarcoplasmic reticulum; thrombospondin complex
Genetic constraint (gnomAD): Loss-of-function variants: 88 observed, 111.08 expected, observed/expected ratio (o/e) 0.79, 90% interval 0.67 to 0.95. The upper end of that interval is the gene's LOEUF score, 0.95, which puts it in group 4 of 6, group 1 being the genes least tolerant of losing a copy. Missense variants: 1,072 observed, 1,223.5 expected, observed/expected ratio (o/e) 0.88, 90% interval 0.83 to 0.92. Synonymous variants: 457 observed, 477.18 expected, observed/expected ratio (o/e) 0.96, 90% interval 0.89 to 1.03.
Homologues: Orthologues: chimpanzee THBS4 (99% identical), dog THBS4 (93% identical), rat Thbs4 (93% identical), macaque THBS4 (93% identical), mouse Thbs4 (93% identical), guinea pig THBS4 (91% identical), pig THBS4 (91% identical), rabbit THBS4 (89% identical), tropical clawed frog thbs4 (74% identical), zebrafish thbs4b (69% identical), zebrafish thbs4a (63% identical), Drosophila melanogaster Tsp (42% identical). Paralogues in human: THBS3 (61% identical), COMP (55% identical), THBS1 (42% identical), THBS2 (42% identical), ISM1 (9% identical).
Diseases named in the same sentence as THBS4 in open-access papers:
THBS4 is named in the same sentence as 127 diseases in open-access papers, as found by Europe PMC text mining. Sharing a sentence is not in itself a finding about the gene and the disease. The quoted sentences say what the papers report.
breast cancer (16 papers, 2016 to 2025). A primary or metastatic malignant neoplasm involving the breast. "High levels of THBS4 have been found to be significantly related to cancer-associated ECM in breast cancer tissue, and the high expression levels of THBS4 in cancer-associated fibroblasts in Lauren diffuse-type gastric adenocarcinoma support its use as a biomarker." (PMID 36241983, 2022). "Moreover, the NHS and THBS4 gene expression are associated with RFS in breast cancer patients according to Kaplan–Meier plotter." (PMID 32679794, 2020). "According to Kaplan–Meier plotter, low expression of NHS, THBS4, and SLITRK6 is associated with poor relapse-free survival (RFS) in breast cancer patients." (PMID 32679794, 2020). "Recent studies have identified THBS4 as a regulatory of multiple cancers, such as prostate cancer, breast cancer and some types of gastric cancers." (PMID 28177895, 2017). "In addition, KIF14-positive cells show upregulation of the THBS4 (thrombospondin 4) gene that is known to possess proangiogenic and proinflammatory activity in breast cancer." (PMID 32679794, 2020). "This suggests that especially changes in haptoglobin, but also fibrinogen beta chain, thrombospondin-4 and transferrin receptor protein 1 is indicative of metastasis, at least in this breast cancer model, and should be further evaluated as general breast cancer biomarkers." (PMID 31042781, 2019). "Thrombospondin 4 contributes to the activation of stromal responses exhibited during tumour progression and this may facilitate invasion of tumour cells in breast cancer." (PMID 31042781, 2019). "Muppala S recently reported that THBS4 affects the functions of microvascular endothelial cells and promotes angiogenesis in EMT6 mouse breast cancer cells." (PMID 34390328, 2021). "Additionally, the activation of integrin signaling via binding of THBS4 to ITGA2 may contribute to activation of Wnt/β-catenin pathway as ITGA2 has been shown to be instrumental for platelet-induced activation of Wnt/β-catenin signaling in MCF7 breast carcinoma cells." (PMID 34631719, 2021). "Additionally, BPS upregulates genes (THBS4, PPARGC1A, CREB5, COL5A3) related to breast cancer progression." (PMID 33330580, 2020).
cardiac hypertrophy (11 papers, 2017 to 2025). "Bulk RNA sequencing revealed significant upregulation of several biomarkers associated with cardiac hypertrophy in BubR1 hypomorphic hearts, including Thbs4, Acta1, Tnni2, and Myh7." (PMID 40607964, 2025). "However, despite the evidence that Thbs4-mediated ATF6α activation is protective after acute injury, we did not observe that overexpression of Thbs4 mitigated phenotypic changes associated with cardiac hypertrophy." (PMID 30765833, 2019). "On the basis of mouse scRNA-seq data, several subpopulations of fibroblasts, e.g., fibroblast-Thbs4, fibroblast-Wif1, fibroblast-Cd248 and fibroblast-vegfd, were found in hypertrophy heart." (PMID 36805782, 2023). "In our datasets, we identified several fibroblast subclusters reported in previous scRNA-seq study of cardiac hypertrophy induced with Angiotensin II, including fibroblast-Thbs4 and fibroblast-Wif1." (PMID 36805782, 2023). "THBS4 deficiency increased ECM deposition in the heart of mice and contributes to cardiac hypertrophy." (PMID 37079380, 2023). "Consistent with previous reports, activation of fibroblast was evidenced by increased proportions of cluster 2, cluster 6 and cluster 8 (subtypes with high expression of extracellular matrix protein including Comp, Postn, Thbs4) at the stage of cardiac hypertrophy." (PMID 36805782, 2023). "Our results confirm previous work in rodent models of hypoxia, with respect to expression of fetal genes (NPPA, NPPB), fibrotic genes (TGFB2, CTGF, LTBT2), and genes marking cardiac hypertrophy (NPPB, THBS4) in the heart after exposure to hypoxia." (PMID 31960631, 2020). "For instance, THBS4 regulates the production and assembly of collagen, and in the pathological context of cardiac pressure overload, THBS4 prevents excess ECM deposition and myocardial hypertrophy." (PMID 38572485, 2024).
myocardial infarction (11 papers, 2014 to 2025). Gross necrosis of the myocardium, as a result of interruption of the blood supply to the area, as in coronary thrombosis. "Importantly, validation in a murine myocardial infarction (MI) model further corroborated these observations, demonstrating significant upregulation of TIMP1 and THBS4 mRNA expression, alongside downregulation of HCLS1." (PMID 41393260, 2025).
gastric cancer (10 papers, 2017 to 2026). A primary or metastatic malignant neoplasm involving the stomach. "THBS4 expression in cancer-associated fibroblasts (CAFs), normal-associated fibroblasts (NFs) and gastric cancer cell lines was examined by western blotting." (PMID 31703077, 2019). "THBS4 from CAFs is associated with the metastasis of cancer cells, and is a useful prognostic indicator for gastric cancer patients." (PMID 31703077, 2019). "THBS4 from CAFs might be associated with the invasion of cancer cells, and THBS4 is also a useful prognostic indicator for gastric cancer patients, especially for those with stage I or stage III cancer." (PMID 31703077, 2019). "Except for SCRG1 and THBS4, the other hub genes were expressed at lower levels in the gastric cancer tissues than in the normal tissues." (PMID 35392086, 2022). "Migration of BM-MSCs to the site of chronic mucosal injury induced the upregulation of THBS4, which was also evident in human gastric cancer and correlated with increased blood vessel formation and worse outcome." (PMID 34390328, 2021). "THBS4 mRNA and protein levels were upregulated in human gastric cancer cells compared to normal gastric cells, and THBS4 overexpression promoted the migration and invasion of gastric cancer cells." (PMID 34804159, 2021). "Here, we found that THBS4 is upregulated in gastric cancer and overexpression of THBS4 predicts shorter overall survival of gastric cancer patients." (PMID 34804159, 2021). "Few investigations have examined the clinicopathological significance of THBS4, and we conducted the present study to evaluate the clinicopathological significance of THBS4 expression in gastric cancer, especially in tumor stroma." (PMID 31703077, 2019). "Although it has been reported that THBS4 is highly expressed in cancer stroma, the significance of THBS4 in tumor stroma in the development of gastric cancer has been controversial." (PMID 31703077, 2019). "In conclusion, THBS4 is expressed on CAFs in the microenvironment of gastric cancer, especially in macroscopic type-4 gastric cancer." (PMID 31703077, 2019). "High THBS4 expression in stromal cells was revealed as an independent prognostic factor for gastric cancer patients." (PMID 31703077, 2019). "Correlation between the expression of THBS4 in tumor stromal cells and clinicopathologic features in 584 patients with gastric carcinoma." (PMID 31703077, 2019). "THBS4 from CAFs might be a useful prognostic indicator for gastric cancer patients, especially for those with stage I or III cancer." (PMID 31703077, 2019). "THBS4 is expressed on CAFs in the gastric cancer microenvironment." (PMID 31703077, 2019). "We evaluated the clinicopathologic significance of THBS4 expression in gastric carcinoma (GC)." (PMID 31703077, 2019). "In gastric cancer, THBS2 is positively correlated with THBS1, THBS3, and THBS4." (PMID 34804159, 2021). "Notably, THBS4 was expressed at significantly higher levels in gastric carcinoma than in noncancerous stomach tissues." (PMID 34390328, 2021).
hepatocellular carcinoma (8 papers, 2017 to 2025). A malignant tumor that arises from hepatocytes. "Similar to our findings in PTMC, in hepatocellular carcinoma, bladder cancer and prostate cancer, high expression of THBS4 in tumor cells promoted tumor growth, proliferation and invasion." (PMID 40303998, 2025). "Overexpression of THBS4 was also highly correlated with advanced stage vascular invasion in hepatocellular carcinoma." (PMID 34943605, 2021). "However, THBS4 has been suggested as a valuable gene and regulator and has been found to target several cancers including, breast, gastric, and hepatocellular carcinoma." (PMID 34502094, 2021).
colorectal cancer (7 papers, 2010 to 2024). A primary or metastatic malignant neoplasm that affects the colon or rectum. "Recently, it was found that there are increased levels of THBS4 in colorectal cancer patients and it is highly associated with PDGFRβ expression in tumor tissues compared to normal tissues." (PMID 34502094, 2021). "THBS4 is upregulated in colorectal cancer and is associated with tumor progression." (PMID 34804159, 2021). "For instance, the tumor-suppressing role of THBS4 on the proliferation of colorectal cancer was reported, but a pro-tumorigenic role for THBS4 was also reported in prostate and gastric caners." (PMID 35456219, 2022). "In contrast, other studies have reported lower levels of THBS4 protein and hypermethylation of THBS4 in colorectal cancer, cutaneous T-cell lymphoma, and bladder cancer with an indication of epigenetic silencing in these tumors." (PMID 35008203, 2021). "We identified that PDGFRβ and THBS4 are overexpressed in tumor tissues of colorectal cancer patients, and that PDGF-D expression increased after TGFβ treatment in the colon cancer cell line DLD-1." (PMID 32899998, 2020). "Although one controversial study suggested that THBS4 may act as a tumor suppressor gene in colorectal cancer, considering all of the results in the other types of cancer, higher expression of THBS4 is more likely associated with tumor development." (PMID 34502094, 2021). "In colorectal cancer, THBS4 is critical in PDGFRβ-mediated tumor progression." (PMID 34804159, 2021). "THBS4 shows increased methylation in colorectal cancer, but this is not strongly associated with altered gene expression, either because methylation has not always reached a critical level or because other factors influence THBS4 expression." (PMID 20846368, 2010). "In this study, using cell assay techniques, transcript and protein analyses in colon cancer patient tissue, and the cell line, we show that PDGFRβ stimulation by TGFβ and PDGF-D increases the THBS4 secretion via IP3R and STIM1 in colorectal cancer." (PMID 32899998, 2020). "The aims of this study were to evaluate the deregulation of THBS4 in a series of colorectal cancers, to examine correlations with CIMP, to probe the effect of forcing THBS4 protein expression in CRC cell lines and to examine the mechanism of THBS4 deregulation." (PMID 20846368, 2010). "Forced over-expression of THBS4 in multiple colorectal cancer cell lines, regardless of their basal THBS4 expression, consistently reduced colony forming ability." (PMID 20846368, 2010).
heart failure (7 papers, 2017 to 2025). Inability of the heart to pump blood at an adequate rate to meet tissue metabolic requirements. "Consistent with our mouse data, cluster 6 (subtypes with high expression of extracellular matrix protein including POSTN, THBS4) at heart failure which showed elevated capacity of ECM organization, extracellular structure organization." (PMID 36805782, 2023). "Recent research has indicated that THBS4 is involved in severe hypertrophic cardiomyopathy and heart failure pathogenesis." (PMID 32631246, 2020). "Furthermore, we observed the proportion of markers associated with fibroblasts (VIM, POSTN, DDR2, THBS4, COL1A1, COL1A2, FN1) were significantly higher in heart failure than the control group in the human data, which were consistent with that in mice." (PMID 36805782, 2023). "THBS4 is implicated in severe HCM and heart failure pathogenesis." (PMID 38077583, 2023). "Consistent with above data, cluster 1 (subtypes with high expression of extracellular matrix protein including DDR2, THBS4, FN1, POSTN) at heart failure which involved in ECM organization, extracellular structure organization." (PMID 36805782, 2023). "Several subpopulations of fibroblasts such as fibroblast-THBS4, fibroblast-FN1, fibroblast-POSTN were also found in human heart increasing with heart failure, which is consistent with our results in mice." (PMID 36805782, 2023). "In addition, as shown in the volcano plot, the levels of active fibroblast markers (POSTN, THBS4, CILP, and FN1) were increased in the heart failure group." (PMID 39198543, 2024). "In addition, we found that active fibroblast markers (POSTN, THBS4, CILP, and FN1) were significantly elevated in the heart failure group." (PMID 39198543, 2024). "Previous study shows that up-regulation of THBS1 and THBS4 may lead to matri-cellular protein deposition, and subsequently resulting in DCM, heart failure or death." (PMID 30115125, 2018).